IL32 (interleukin 32)
Diseases named in the same sentence as IL32 in open-access papers (continued):
Sharing a sentence is not in itself a finding about the gene and the disease.
psoriasis (12 papers, 2011 to 2025). An autoimmune condition characterized by red, well-delineated plaques with silvery scales that are usually on the extensor surfaces and scalp. "Several studies have shown an association between IL-32 levels and degrees of inflammation in AD, psoriasis, HS, and AA." (PMID 37727785, 2023). "More importantly, the results of this study, for the first time, provide evidence of a strong association of IL-32 levels with the peripheral blood of psoriasis patients." (PMID 29538330, 2018). "Our novel findings support an association between elevated levels of IL-32 and psoriasis." (PMID 29538330, 2018). "Therefore, it is clear that IL-32 and its isoforms are implicated in contributing to the pathogenesis of psoriasis, which may be targeted to offer new therapeutic options for psoriasis." (PMID 29538330, 2018). "It is noteworthy that the major isoforms of IL-32, namely IL-32α, IL-32β, IL-32γ, and IL-32δ have been detected in both skin and blood samples from individuals with AD, psoriasis, and HS." (PMID 37727785, 2023). "In comparison between patients with PsA and those with psoriasis, the levels of IL-32 in plasma from patients with PsA were higher than that from patients with psoriasis." (PMID 36875066, 2023). "Plasma levels of IL-32 are elevated in patients with PsA compared to those in healthy controls, and notably higher than in patients with psoriasis alone." (PMID 37511421, 2023). "A study comparing patients with asthma, psoriasis, and AD to healthy subjects found that IL-32 was higher in asthmatic and AD patients’ serum." (PMID 35281066, 2022). "The increased levels of IL-32α observed in psoriatic patients in the present study, together with other isoforms of IL-32, provide further support for the involvement of IL-32 in psoriasis." (PMID 29538330, 2018). "The data reveal striking differences of IL-32 mRNA in the peripheral blood of psoriasis patients and healthy humans (p = 0.001)." (PMID 29538330, 2018). "In this regard, further studies are recommended to comprehensively explore the therapeutic potential of IL-32 and its isoforms in psoriasis." (PMID 29538330, 2018). "After IL-32α, the second most active isoform of IL-32 was found to be IL-32γ, although IL-32β and IL-32δ were also biologically active in psoriasis." (PMID 29538330, 2018). "The data also pointed out that IL-32α was more significantly expressed as compared with other isoforms of IL-32, indicating that the major proinflammatory activity of IL-32 was derived from IL-32α in psoriasis." (PMID 29538330, 2018). "In an attempt to understand the role of IL-32 in the pathogenesis of psoriasis, this is the first study to determine the role of IL-32 in the peripheral blood of psoriatic patients." (PMID 29538330, 2018). "In conclusion, our results clearly show a significant increase of IL-32 levels in patients with chronic plaque psoriasis, suggesting that IL-32 is involved in the induction of inflammation in psoriasis." (PMID 29538330, 2018). "Additionally, IL-32, IL-33, and IL-36α levels are increased in both the plasma and lesional skin of patients with psoriasis." (PMID 40731810, 2025). "In psoriasis IL-32 expression is increased in infiltrating Tregs, Th cells and cytotoxic T cells, although there are conflicting reports of whether IL-32 is increased in the serum." (PMID 40977709, 2025). "Interestingly, the levels of IL-32 in the plasma and IL-32 mRNA in the PBMCs from patients with psoriasis are already higher than those from healthy controls." (PMID 36875066, 2023). "One study showed increased IL32 gene expression in psoriasis lesions compared to healthy controls." (PMID 37727785, 2023). "In addition, expression of the IL32 gene in human mast cells (LAD2) was induced upon stimulation with substance P, a mediator released in the skin from sensory nerve endings, indicating potential induction of IL-32 during a neurogenic flare in psoriasis." (PMID 37727785, 2023).
psoriasis (continued). "In addition to its role in AD, IL-32 has also been shown to be involved in other inflammatory skin diseases such as psoriasis, HS and AA." (PMID 37727785, 2023). "Most importantly, elevated IL-32 has also been reported in skin biopsies of psoriasis patients." (PMID 29538330, 2018). "However, the potential of interleukin (IL)-32 and its isoforms to contribute to the pathogenesis of psoriasis remains unexplored." (PMID 29538330, 2018). "The data also suggest that a major proinflammatory response of IL-32 may derive from IL-32α isoform in psoriasis." (PMID 29538330, 2018). "Therefore, IL-32 could be a biomarker for assessing disease activity of PsA and for detecting development of PsA in patients with psoriasis." (PMID 36875066, 2023). "Besides its role in AD, IL-32 has also been proposed as a biomarker for psoriasis, AA and HS." (PMID 37727785, 2023). "In summary, IL-32 protein expression seems to be increased in HS and AA lesions compared to healthy skin, whereas only IL32 gene expression is increased in psoriasis." (PMID 37727785, 2023). "Since KC apoptosis appears to be required for the release of IL-32 in AD, this would explain the low abundance of IL-32 protein in psoriasis and imply that KC-derived IL-32 may not be involved in the pathogenesis of psoriasis." (PMID 37727785, 2023). "However, the role of IL-32 in the peripheral blood has never been investigated in psoriasis." (PMID 29538330, 2018).
asthma (11 papers, 2018 to 2025). "Moreover, increased serum levels of IL-32 have been associated with various auto-immune and allergic diseases, namely type 2 diabetes, asthma, allergic rhinitis, and systemic lupus erythematosus." (PMID 34829759, 2021). "To date, the molecular mechanism underlying the role of IL-32 in asthma remains to be elucidated." (PMID 29940981, 2018). "Although the composition of the cell subsets was similar between the groups, increased expression of JAK1, the long noncoding RNA NEAT1, and IL32 was noted in specific cell types of patients with severe asthma." (PMID 39672815, 2024). "The possibilities of using IL-32 as an airway inflammation biomarker and an asthma therapeutic agent are also evaluated." (PMID 29940981, 2018). "Additional studies should be conducted to investigate the presence of IL-32 isoforms in patients with difference asthma subtypes." (PMID 29940981, 2018). "From this summary of the recent literature, it is clear that the roles of IL-32 in asthma remain controversial based on the inconsistencies in the results from in vivo or in vitro studies." (PMID 29940981, 2018). "This review aims to summarize recent advances in the pathophysiology of asthma and describe the links to IL-32." (PMID 29940981, 2018). "Therefore, they declared the usefulness of using IL-32 serum levels in diagnosis to examine patients with AD or asthma." (PMID 35281066, 2022). "However, several recent studies have found that IL-32 negatively regulates immune function in some immune diseases such as asthma, HIV infection, Alzheimer disease, and non-alcoholic fatty liver disease." (PMID 34414188, 2021). "However, several reports suggested that IL-32 was downregulated in several inflammatory diseases, including asthma, HIV infection disease, neuronal diseases, metabolic disorders, and experimental colitis." (PMID 34414188, 2021). "Accordingly, inhibition of IL-32 signal might be a potential therapeutic direction for asthma treatment." (PMID 29940981, 2018). "These contradictions might be explained by the nature of asthma airway inflammation (heterogeneity, four subtypes) and the functional differences between IL-32 isoforms." (PMID 29940981, 2018). "Interleukin (IL)-32 plays a role in several chronic inflammatory diseases, including severe asthma." (PMID 30257681, 2018). "Here we present recent advances with regard to the role of IL-32 in the pathophysiology of asthma." (PMID 29940981, 2018). "IL-32 has increasingly been suggested as a key player in the pathophysiology of asthma." (PMID 29940981, 2018). "Notably, the roles of IL-32 may be different for each subtype of asthma, and these should be further investigated." (PMID 29940981, 2018). "Because the supernatant of IL-32 siRNA-transfected normal human bronchial epithelial cells increased in vitro angiogenesis of human umbilical vein endothelial cells, IL-32 might be also an inhibitor of airway remodeling in asthma patients." (PMID 29940981, 2018). "Targeting of IL-32 signaling might be a potential therapeutic strategy for asthma treatment." (PMID 29940981, 2018). "In Asthma 3, JUN is also repressed while the expression patterns of IL7R, IL32, and CCL5 are more similar to healthy controls." (PMID 41550933, 2025). "In addition to finding increased expression of JAK1 in unstimulated cells of SA, we found high expression of pro-inflammatory genes including IL32, a cytokine with pro-inflammatory and antiviral activity; genes involved in Th2 inflammation; and CCL4, involved in asthma exacerbations." (PMID 33902571, 2021).
hepatoma (10 papers, 2014 to 2025). "IL-32 was upregulated in hepatoma cell line (HepG2 and Huh7) after exposure to saturated fatty acids, whereas treatment of primary human hepatocytes with IL-32 promoted hepatic IR in vitro." (PMID 40794228, 2025). "Stimulation of hepatoma cell lines with palmitic acid induces cellular stress and IL-32 expression by activating the ERK and p38-MAPK cascade." (PMID 41383621, 2025). "We analyzed the expression of interleukin 32 (IL-32) and chemokine CC ligand 20 (CCL20), which are known to be linked with inflammation and fibrosis, and for their expression in MASLD and hepatoma cells." (PMID 37686029, 2023). "Consistent with this, we have shown increased IL-32 expression in hepatoma cells upon treatment with PA, known to generate ROS, which is mitigated by OA." (PMID 37686029, 2023). "TNF-α and IFN-γ induced IL-32 in primary human hepatocytes and hepatoma cells that regulate the transcription of HBV core promoter by downregulating HNF1-α and HNF4-α." (PMID 33868257, 2021). "In intro cytotoxicity assay demonstrated that NKP30-B7-H6 interaction enhanced IL-32 expression and induced hepatoma cells apoptosis." (PMID 26241657, 2015). "Furthermore, in vitro cytotoxicity assay demonstrated that NKP30-B7-H6 interaction unregulated IL-32 expression and induced hepatoma cells apoptosis." (PMID 26241657, 2015). "To shed light on the role of cellular steatosis for the expression of IL-32 and CCL20 in MASLD, we treated two hepatoma cell lines, HepG2 and Huh7, with palmitic acid (PA, C16:0), known to induce cellular lipid accumulation, lipo-apoptosis and lipo-toxicity." (PMID 37686029, 2023). "Treatment with the saturated fatty acid palmitic acid (PA) induced mRNA and protein expression of IL-32 and CCL20 in hepatoma cells." (PMID 37686029, 2023). "Here, we present data showing increased expression of IL-32 and CCL20 in patients with MASH, as well as their induction by PA in hepatoma cells, likely mediated by oxidative stress and cellular lipid loading." (PMID 37686029, 2023). "In non-hematopoietic cells, IL-32 expression is upregulated in hepatoma cells (Huh7.5), human aortic valve interstitial cells, and the human gastric epithelial cell line." (PMID 41383621, 2025). "On incubation of spheroids composed of human hepatoma cells (HepG2) and immortalized hepatic stellate cells (LX2) with increasing amounts of a mixture of 1:2 palmitic and oleic acid (0–1 mM), we observed a dose dependent increase in IL32 expression." (PMID 38232700, 2024). "Consequently, we analyzed the gene expression of IL-32 and CCL20 in the liver tissue of controls and patients as well as the effect of fatty acids on their expression in hepatoma cells." (PMID 37686029, 2023). "Furthermore, IL-32 induced the apoptosis of Huh7 cells in a dose-dependent manner.Taken together, these data demonstrate that the NKP30-B7-H6 interaction induced IL-32 expression and enhanced NK cell-mediated cytotoxicity against hepatoma cells." (PMID 26241657, 2015). "Although the secretory pathway of IL-32 and its cell surface receptor for signal transduction is still not completely understood, it has been reported that overexpressed or induced IL-32 is not secreted from hepatoma cells or hepatocytes infected with hepatitis B virus (HBV)." (PMID 37686029, 2023).
allergic rhinitis (9 papers, 2012 to 2025). Inflammation of the nasal mucous membranes caused by an IgE-mediated response to external allergens. "IL-32 has been assessed in association with some other diseases, including allergic rhinitis, rhinosinusitis, lupus erythematosus and other autoimmune disorders." (PMID 29134126, 2017). "This compound inhibited allergic responses via the regulation of the production of IL-32 and thymic stromal lymphopoietin and nasal mucosa caspase-1 activity in a murine allergic rhinitis model." (PMID 26694364, 2015). "Similarly, the expression (both mRNA and protein) of IL-32 in nasal mucosa is increased in allergic rhinitis (AR) patients." (PMID 29940981, 2018). "Moreover, in the patients with seasonal allergic rhinitis, dsRNA challenge increased IL-32 expression when compared to saline challenge at the height of the pollen season." (PMID 29940981, 2018).
colon cancer (9 papers, 2014 to 2025). "We found heterozygosity for the LP MVP c.2296C>T p.Arg766X and IL32 c.515_516insG p.Asp172Glufs* variants in both the index case #11 and her mother, in whom colon cancer had been diagnosed at an early age." (PMID 40995433, 2025). "As reported, the expression of IL-32 protein is remarkably increased in colorectal and colon cancer tissues, and its expression level also reflects both disseminated disease and survival." (PMID 36505098, 2022). "The upregulation of IL-32 for colon cancer and prostate cancer can enhance the killing function of NK cells." (PMID 34414188, 2021). "When analyzed with reference to cancer type, IL32 showed strong positive correlation with Ki67 in gastric tumors (r = 0.72, p = 0.009) and only a weaker tendency in colonic tumors (r = 0.41." (PMID 33020452, 2020).
systemic lupus erythematosus (9 papers, 2015 to 2024). An autoimmune multi-organ disease typically associated with vasculopathy and autoantibody production. "We then confirmed that these genes, such as IL32, CD226, CDKN1A, and PTPRN2 were similarly hypomethylated in lupus patients of African-American compared to European-American descent." (PMID 26609326, 2015).
diabetes (8 papers, 2019 to 2025). "IL-32 has only recently been identified as an early biomarker in the blood of children from type 1 diabetes-risk families even before autoantibody appearance and diabetes manifestation." (PMID 35122482, 2022). "Furthermore, reporter cell lines infected with enterovirus strains isolated from Network for Pancreatic Organ Donors with Diabetes (nPOD) pancreases exhibited increased IL-32 expression compared to those infected with control enterovirus strains." (PMID 40977709, 2025). "Finally, in a human IL-32γ-expressing transgenic mouse model, when mice expressed human IL-32γ, streptozotocin-induced diabetes was accelerated, highlighting IL-32 as an important biomarker for T1D progression." (PMID 40977709, 2025). "It has been demonstrated that IL32 is highly expressed by CD4+ T cells from people living with T1D, as assessed by single cell sequencing, in response to neo- and native epitopes of diabetes autoantigens." (PMID 40977709, 2025).
leishmaniasis (8 papers, 2014 to 2025). Infectious disease that is transmitted through the bite of hematophagous female phlebotomine sand flies. "In this context, the present review report briefly discusses the data retrieved from the studies conducted on IL-32 in leishmaniasis in humans and mice to highlight the current challenges to understanding the role of IL-32 in leishmaniasis." (PMID 35309341, 2022). "As all cytokines evaluated in this study have been shown to be involved in immunopathogenesis of leishmaniasis and in the parasite control, the present data indicate a pivotal role of IL-32 in the induction of cytokine production after Leishmania spp." (PMID 32023240, 2020). "Next steps will include primary human macrophages to better understand the role of IL-32 in human leishmaniasis." (PMID 28241012, 2017). "We showed that the mRNA expression of IL-32, in particular IL-32γ was similarly up-regulated in lesions of cutaneous (CL) or mucosal (ML) leishmaniasis patients." (PMID 24884781, 2014). "IL-32 is expressed in several cells present in the leishmaniasis lesions (epithelial and endothelial cells, mononuclear cells, giant cells)." (PMID 24884781, 2014). "IL-32-matured and activated dendritic cells induce T helper (Th) lymphocyte differentiation into Th1 and Th17 cells, which are important cells to control leishmaniasis." (PMID 28241012, 2017). "Thus, the exact mechanism in how IL-32 isoforms modulates the production of proinflammatory cytokines and whether these connections contributes to immunopathology or wound healing remains to be investigated in leishmaniasis." (PMID 32023240, 2020). "Data indicate that IL-32 serves as a determinant of gene expression profile at the level of bone marrow progenitors by mediating the trained immunity induced by β-glucan or BCG and conferring protection against leishmaniasis." (PMID 35309341, 2022). "It is important to highlight that murine models of leishmaniasis are not a reliable landscape of the immune responses against Leishmania parasites because mice do not produce IL-32." (PMID 28709468, 2017). "Until now, the presence of IL-32 was not evaluated in leishmaniasis and in ATL IL-32 could be a crucial mediator between epithelium and inflammatory cells." (PMID 24884781, 2014).
lung adenocarcinoma (8 papers, 2014 to 2024). A carcinoma that arises from the lung and is characterized by the presence of malignant glandular epithelial cells. "IL32 encodes a cytokine that is up-regulated in lung adenocarcinomas and is correlated with lymph node metastasis." (PMID 27933110, 2016). "To test this possibility, we evaluated the role of IL-32 in A549 lung adenocarcinoma cells and the mechanisms of action in relation to the influence on EMT and ER stress." (PMID 33097029, 2020). "Human lung adenocarcinoma A549 cells were treated with recombinant human (rh)IL-32, IL-32 siRNA and EMT inducer tunicamycin, or 4-phenylbutyric acid (4-PBA), respectively." (PMID 33097029, 2020). "In lung adenocarcinomas, IL32 is highly expressed in both tumor cells and infiltrating leukocytes leading investigators to suggest that both the lung tumor cells and tumor infiltrating leukocytes are involved in tumor progression." (PMID 25100201, 2014). "Moreover, this work has identified several novel recurrent mutations in genes not typically associated with lung adenocarcinoma, which are each present in a significant subset of TCGA lung adenocarcinoma patients (e.g. IL32, LOC650368, HSD17B7P2 and RPSA)." (PMID 27933110, 2016). "IL32 and ZC3H13 also play an important role in tumorigenesis and metastasis of lung adenocarcinoma." (PMID 33000861, 2020).